MMD2 (monocyte to macrophage differentiation associated 2)
Synonyms: PAQR10
Tractability: Antibody: UniProt predicts a signal peptide or a membrane-spanning region. PROTAC: its protein half-life has been measured.
Gene: Protein-coding gene on chromosome 7 (4,905,989 to 4,959,212, reverse strand). Ensembl gene ENSG00000136297.
Subcellular location: Golgi apparatus membrane
Gene Ontology:
Molecular function: protein kinase activity
Biological process: positive regulation of neuron differentiation; positive regulation of protein kinase activity; positive regulation of Ras protein signal transduction; regulation of protein localization
Cellular component: Golgi membrane; perinuclear region of cytoplasm; membrane
Genetic constraint (gnomAD): Loss-of-function variants: 30 observed, 30.1 expected, observed/expected ratio (o/e) 1, 90% interval 0.75 to 1.35. The upper end of that interval is the gene's LOEUF score, 1.35, which puts it in group 5 of 6, group 1 being the genes least tolerant of losing a copy. Missense variants: 364 observed, 302.3 expected, observed/expected ratio (o/e) 1.2, 90% interval 1.1 to 1.31. Synonymous variants: 129 observed, 116.07 expected, observed/expected ratio (o/e) 1.11, 90% interval 0.96 to 1.29.
Homologues: Orthologues: pig MMD2 (97% identical), mouse Mmd2 (96% identical), rat Mmd2 (96% identical), macaque MMD2 (94% identical), chimpanzee MMD2 (94% identical), rabbit MMD2 (92% identical), zebrafish MMD2 (69% identical), zebrafish mmd2b (69% identical), zebrafish mmd2a (53% identical), Drosophila melanogaster AdipoR (19% identical), Caenorhabditis elegans paqr-1 (18% identical), Caenorhabditis elegans K11C4.2 (13% identical). Paralogues in human: MMD (69% identical), PAQR5 (22% identical), ADIPOR1 (20% identical), ADIPOR2 (20% identical), PAQR8 (19% identical), PAQR6 (19% identical), PAQR3 (17% identical), PAQR7 (17% identical), PAQR9 (16% identical), PAQR4 (15% identical).
Diseases named in the same sentence as MMD2 in open-access papers:
MMD2 is named in the same sentence as 17 diseases in open-access papers, as found by Europe PMC text mining. Sharing a sentence is not in itself a finding about the gene and the disease. The quoted sentences say what the papers report.
colon cancer (1 paper, 2014).
periodontitis (1 paper, 2025). An acute or chronic inflammatory process that affects the tissues that surround and support the teeth. "Knock-in mice with equivalent MMD2 variants to those found in patients developed ligation-induced periodontitis and recapitulated the symptoms." (PMID 40663042, 2025). "Our studies revealed that monoallelic mutations in MMD2 underlie the impairment of neutrophil chemotaxis, which leads to the development of autosomal dominant aggressive periodontitis." (PMID 40663042, 2025). "The knock-in and knockout mice exhibited alveolar bone loss by ligature-induced periodontitis, along with impaired fMLP-induced chemotaxis, as found in the patients with MMD2 mutation." (PMID 40663042, 2025). "We here identified monoallelic mutations, p.A116V and p.R126P, in the monocyte to macrophage differentiation-associated 2 (MMD2) gene, which encodes MMD2, in two unrelated families with aggressive periodontitis." (PMID 40663042, 2025). "Monoallelic mutations, p.A116V and p.R126P, in MMD2 disturb fMLP-induced activation of Ras/ERK signaling and underlie the impairment of neutrophil chemotaxis, which leads to the development of the autosomal dominant form of aggressive periodontitis." (PMID 40663042, 2025).
brain diseases (1 paper, 2024). "Among the genes annotated to SOX2-bound elements, numerous have been associated with astrogliosis and reactive astrocyte proliferation after TBI or other brain diseases, such as Nr2e1, Mmd2, Wnt7a, and Akt2." (PMID 38672150, 2024).
MMD2 also shares sentences with these, for which no sentence is quoted: breast carcinoma (1 paper); cardiomyopathy (1); congenital myopathy (1); distal myopathy (1); glioma (1); Idiopathic inflammatory myopathies (1); infection (1); MELAS (1); Metabolic myopathies (1); muscular dystrophy (1); Myofibrillar myopathies (1); myopathy (1); nemaline myopathy (1); Welander distal myopathy (1).